SWI5 (SWI5 homologous recombination repair protein)
Description:
Component of the SWI5-SFR1 complex, a complex required for double-strand break repair via homologous recombination.
Synonyms: C9orf119; SAE3; bA395P17.9
Gene: Protein-coding gene on chromosome 9 (128,275,379 to 128,316,123, forward strand). Ensembl gene ENSG00000175854.
Subcellular location: Nucleus
Subcellular location (Human Protein Atlas): Cytosol; Nucleoplasm
Genetic constraint (gnomAD): Loss-of-function variants: 10 observed, 15.23 expected, observed/expected ratio (o/e) 0.66, 90% interval 0.4 to 1.11. The upper end of that interval is the gene's LOEUF score, 1.11, which puts it in group 4 of 6, group 1 being the genes least tolerant of losing a copy. Missense variants: 152 observed, 163.58 expected, observed/expected ratio (o/e) 0.93, 90% interval 0.81 to 1.06. Synonymous variants: 59 observed, 64.05 expected, observed/expected ratio (o/e) 0.92, 90% interval 0.75 to 1.14.
Homologues: Orthologues: chimpanzee SWI5 (99% identical), pig SWI5 (82% identical), dog SWI5 (80% identical), rabbit SWI5 (80% identical), guinea pig SWI5 (75% identical), mouse Swi5 (62% identical), rat Swi5 (62% identical), tropical clawed frog swi5 (44% identical), zebrafish swi5 (41% identical), rat AC134087.1 (37% identical).
Diseases named in the same sentence as SWI5 in open-access papers:
SWI5 is named in the same sentence as 1 disease in open-access papers, as found by Europe PMC text mining. Sharing a sentence is not in itself a finding about the gene and the disease. The quoted sentences say what the papers report.
cancer (1 paper, 2015). A tumor composed of atypical neoplastic, often pleomorphic cells that invade other tissues. "The top pair of genes from the mRNA expression profile was MYO3A, a previously identified cancer gene and SWI5, a recombination repair homolog." (PMID 26138921, 2015).